SMAD5 (SMAD family member 5)
Diseases named in the same sentence as SMAD5 in open-access papers (continued):
Sharing a sentence is not in itself a finding about the gene and the disease.
schizophrenia (5 papers, 2008 to 2024). A major psychotic disorder characterized by abnormalities in the perception or expression of reality. "Moreover, the alterations in measurable proteins in the OE revealed that the protein SMAD5 (mothers against decapentaplegic homolog 5) is a biomarker associated with a cognitive deficit in schizophrenia." (PMID 38654728, 2024).
bladder cancer (4 papers, 2021 to 2024). "In bladder cancer, circRHOT1 can induce SMAD5 expression to regulate tumorigenic properties and NK cell-mediated toxicity by targeting miR-3666." (PMID 36497344, 2022). "The aim of our study was to validate the way of long noncoding RNA (lncRNA) KCNMB2-AS1 on the metabolism and growth of bladder cancer cells by miR-3194-3p/SMAD5." (PMID 34026626, 2021). "Jointly, our study served as a proof that KCNMB2-AS1 may act as an oncogenic lncRNA to stimulate the development of cancer through miR‐3194-3p/SMAD5 pathway and enjoy a great possibility to be a therapeutic target and promising biomarker for bladder cancer." (PMID 34026626, 2021). "Besides, the mechanism of KCNMB2-AS1–miR‐3194-3p–SMAD5 axis may have different effects on different stages of bladder cancer, but this has not been further studied in our research." (PMID 34026626, 2021).
cholangiocarcinoma (4 papers, 2020 to 2025). A carcinoma that arises from the intrahepatic biliary tree (intrahepatic cholangiocarcinoma) or from the junction, or adjacent to the junction, of the right and left hepatic ducts (hilar cholangiocarcinoma). "LINC01410 regulates miR‐124‐3p to increase the SMAD5 expression, elevating cholangiocarcinoma cell proliferation, and migration rates." (PMID 32886453, 2020). "Studies on cholangiocarcinoma (CCA) have demonstrated that LINC01410 acts as a sponge for miR-124-3p, upregulating SMAD5, thereby promoting the proliferation, invasion, and migration of CCA cells and tissues." (PMID 41472748, 2025).
Infertility (4 papers, 2012 to 2021). "BMP7 and phosphorylation of Smad5 were also detected, and the recovery of infertility function in treated mice was evaluated." (PMID 33736694, 2021). "A 6-month fertility trial indicated that conditional deletion of Smad1 resulted in normal fertility, conditional deletion of Smad5 resulted in subfertility, whereas double conditional deletion of Smad1/5 resulted in infertility." (PMID 34099644, 2021). "Deletions of Smad1 and Smad5 lead to infertility and ovarian cancer in mice." (PMID 22496700, 2012). "Double conditional deletion of SMAD1/5 led to infertility, whereas single conditional deletion of SMAD1 or SMAD5 resulted in normal fertility or subfertility, respectively." (PMID 34099644, 2021). "Moreover, conditional double deletion of SMAD1 and SMAD5 or triple deletion of SMAD1, SMAD5, SMAD8 led to infertility and granulosa cell tumor development in mice." (PMID 34069790, 2021).
lung carcinoma (4 papers, 2012 to 2024). "Among these tagSNPs, there was a consistently significant association between Smad5 rs12719482 and the risk of lung cancer in the three population sources (P < 0.05)." (PMID 39578779, 2024). "In the present study, we build a BCP model with Lewis lung cancer cells, aiming to investigate the association between miR-93 and Smad5 and the effect of miR-93 and Smad5 on morphine tolerance." (PMID 27438143, 2016). "Smad5 rs12719482 polymorphism may be a potential etiologic factor for lung cancer in patients." (PMID 39578779, 2024). "What’s more, they found four target genes of miR-155 including HBP1, TJP1, SMAD5 and PRKAR1A involved in the oxidative stress process of lung cancer." (PMID 31727002, 2019). "We will also explore the related signaling pathways and the mechanisms of Smad5 in respiratory diseases, including chronic obstructive pulmonary disease (COPD), bronchial asthma, pulmonary arterial hypertension(PAH), lung cancer, and idiopathic pulmonary fibrosis (IPF)." (PMID 39578779, 2024). "In addition, knockdown of FLJ20420 expression also significantly increased the expression of PRKCBP2, TGFBR1, TGFB2, CLCN4, TRAF3, MYLK and ACTA2, while decreasing the expression of SMAD5 and prot-LBC, resulting in an increased apoptotic potential in FLJ20420-silenced lung cancer cells." (PMID 22567091, 2012).
asthma (3 papers, 2020 to 2024). "In our study, EP300, ID1, ID3, SMAD2, and SMAD5 were DC with a loss of connectivity, whereas SMAD7 exhibited a network connectivity gain due to asthma." (PMID 34257337, 2021). "Smad5 has been relatively under-researched in the context of asthma." (PMID 39578779, 2024). "Currently, there is no direct research investigating the relationship between Smad5 and pro-inflammatory cytokines in the context of asthma." (PMID 39578779, 2024). "However, TGF-β1 stimulation strongly decreased Smad1 but not Smad5 contents in HBFs from patients with asthma." (PMID 33020537, 2020).
B-cell lymphoma (3 papers, 2012 to 2017). "SMAD5 negatively regulates cell proliferation during embryonic hematopoiesis, in B-cell lymphoma, and it induces cell cycle arrest in response to shear stress in tumor cell lines." (PMID 28899340, 2017). "While SMAD5 was found to be directly inhibited by miR-155 in B cell lymphoma cells." (PMID 23091595, 2012).
bone cancer (3 papers, 2016 to 2025). A primary or metastatic malignant neoplasm affecting the bone or articular cartilage. "SMAD5 also participates in the development of morphine tolerance in bone cancer pain mouse models by regulating miR-93-5p." (PMID 40852585, 2025). "miR-93 and its downstream target Smad5 were demonstrated to be correlated with morphine tolerance in bone cancer pain mouse model." (PMID 29615865, 2018). "In this study, we aim to find out the role of microRNA-93-5p (miR-93) and Smad5 in morphine tolerance in mouse models of bone cancer pain (BCP)." (PMID 27438143, 2016). "Overall, Up-regulation of miR-93 may contribute to the progression of morphine tolerance by targeting Smad5 in mouse bone cancer pain." (PMID 29615865, 2018).
granulosa cell tumor (3 papers, 2019 to 2021). A slow-growing, malignant tumor, characterize by the presence of granulosa-like cells and Call-Exner bodies, that is almost always found in the ovary. "For R-Smads, SMAD1 regulated COV434 cell (a human granulosa cell tumor-derived cell line) apoptosis, and SMAD5 suppressed human granulosa cell apoptosis via the FasL-Fas pathway, but SMAD8 has not been reported to regulate GC apoptosis." (PMID 31167348, 2019).
lymphoma (3 papers, 2011 to 2014). A malignant (clonal) proliferation of B- lymphocytes or T- lymphocytes which involves the lymph nodes, bone marrow and/or extranodal sites. "MiR-155 has also been reported to be involved in the development of lymphoma by targeting SMAD5 (SMAD family member 5) and SHIP1 (inositol polyphosphate-5-phosphatase)." (PMID 21541331, 2011). "Furthermore, it has been shown that miR-155 targets Smad2 mRNA in the monocytic cell line THP1 as well as Smad5 mRNA in lymphoma cells." (PMID 23554893, 2013).
nasopharyngeal carcinoma (3 papers, 2021 to 2025). A carcinoma arising from the nasopharyngeal epithelium. "Smad5 inhibits the growth and metastasis of nasopharyngeal carcinoma by binding to miR-384 and inhibiting the Wnt/β-catenin axis." (PMID 40852585, 2025). "SMAD5 downregulation inhibited cell proliferation, invasion and migration, and reversed EMT, enhanced apoptosis of nasopharyngeal carcinoma cells, which is consistent with our study." (PMID 33371778, 2021).
osteoporosis (3 papers, 2017 to 2024). A condition of reduced bone mass, with decreased cortical thickness and a decrease in the number and size of the trabeculae of cancellous bone (but normal chemical composition), resulting in increased fracture incidence. "It is well known that deregulation of SMAD5 participates in the pathogenesis of osteoporosis, and increasing SMAD5 expression can promote bone formation during osteoporosis." (PMID 39075522, 2024). "SMAD5 has been proven to facilitate osteogenic differentiation and participate in osteoporosis pathogenesis." (PMID 39075522, 2024). "Circ_0001825 promoted hMSC viability and osteogenic differentiation via miR-1270/SMAD5 axis, suggesting the potential involvement of circ_0001825 in osteoporosis." (PMID 37674252, 2023). "Moreover, several miRNAs, such as miR-24-1-5p and miR-451a, regulate osteoblast function during osteoporosis by targeting SMAD5." (PMID 39075522, 2024). "Moreover, recent evidence suggests that SMAD5 has close relevance to the pathogenesis of osteoporosis through its regulatory functions in osteogenic differentiation and bone formation." (PMID 39075522, 2024). "In all, our data first demonstrated that circ_0001825 contributed to the viability and osteogenic differentiation in hMSCs via activating SMAD5 through sequestering miR-1270, providing a new insight into the development of circRNA-based therapeutics in osteoporosis intervention." (PMID 37674252, 2023). "Thus, upregulation of SPI1 and SMAD5 expression may induce bone formation during osteoporosis." (PMID 39075522, 2024). "Here, we demonstrate that the SPI1/SMAD5 cascade is capable of inducing osteogenic differentiation of MC3T3-E1 cells, the murine pre-osteoblast cells that have been widely applied for the research of osteogenic differentiation in osteoporosis." (PMID 39075522, 2024). "Furthermore, these Ca extracts increased the expression levels of BMP-2, Wnt3a, SMAD5, RUNX2, osteocalcin and COL-1 in an in vivo model of osteoporosis, while they decreased TRAP, cathepsin K and RANK expression levels." (PMID 28513557, 2017).
cognitive deficit (2 papers, 2021 to 2024). "Indeed, in recent studies, whole-exome sequencing has revealed that SMAD5 is one of the candidate genes of SCZ and another study showed that SMAD5 was associated with cognitive deficits in SCZ patients." (PMID 34955918, 2021).
colorectal cancer (2 papers, 2016 to 2023). A primary or metastatic malignant neoplasm that affects the colon or rectum. "It thereby activates the transcription of the effector SMAD5, and then strengthens the transduction of TGF-β signaling pathway that promotes the survival, invasion and metastasis of colorectal cancer cells." (PMID 27177089, 2016). "This study found that SMAD5 and SMAD6 were significantly overexpressed in colorectal cancer." (PMID 36969909, 2023).
dengue (2 papers, 2015 to 2019). "A recent study showed that analysis of seven genes (LOC286087, SLC4A4, PSPH, MYOM2, CACNA2D3, CD244 molecule, SMAD5) could possibly predict severe dengue since their expression profile was significantly lower in DHF patients compared to patients with DF." (PMID 26462910, 2015). "In addition, host genetic markers, such as the genes LOC286087, MYOM2, CACNA2D3, PSPH, SMAD5, SLC4A4D, and CD244 molecule, with reduced expression in DHF than in DF can be used as predictors of severe dengue." (PMID 31192066, 2019).
esophageal cancer (2 papers, 2022 to 2024). A primary or metastatic malignant neoplasm involving the esophagus. "Moreover, miR-145-5p negatively regulated SMAD5 in esophageal cancer, which in turn can activate the TGF beta signaling pathway." (PMID 36077665, 2022).
idiopathic pulmonary fibrosis (2 papers, 2024). Idiopathic pulmonary fibrosis (IPF) is a nonneoplastic pulmonary disease that is characterized by the formation of scar tissue within the lungs in the absence of any known cause. "We identified over 2,500 O-GlcNAc modified proteins including α-SMA, TIMP1, TIMP3, Smad4, Smad5 and Smad3 have been implicated in pulmonary fibrosis." (PMID 38665916, 2024).
malignant glioma (2 papers, 2017 to 2021). A grade III or grade IV glioma arising from the central nervous system. "It is known that miR-135a can function as a selective killer of malignant glioma by targeting STAT6, SMAD5 and BMPR2." (PMID 28415713, 2017).
osteosarcoma (2 papers, 2018 to 2020). A usually aggressive malignant bone-forming mesenchymal neoplasm, predominantly affecting adolescents and young adults. "Smad1 and Smad5 gene knockdown significantly inhibited SCD-1 protein expression of 20 dynes/cm2 shear force induction in MG63 osteosarcoma cells." (PMID 32630668, 2020). "Smad1 or Smad5 gene knockdown in MG63 osteosarcoma cells blocked the PPARδ protein expression of 20 dynes/cm2 shear force induction." (PMID 32630668, 2020). "Smad1 or Smad5 gene knockdown in human MG63 osteosarcoma cells also blocked the PPARδ transcription activation." (PMID 32630668, 2020).
ovarian carcinoma (2 papers, 2012 to 2016). A malignant neoplasm originating from the surface ovarian epithelium. "For instance, SMAD5 expression is inversely correlated with the prognosis of serious ovarian cancer patients, and BMP-2 stimulated cellular proliferation by inducing phosphorylated SMAD5 (pSMAD5) translocation into the nucleus in ovarian cancer cells." (PMID 27661009, 2016).
prostate carcinoma (2 papers, 2012 to 2023). A carcinoma that arises from epithelial cells of the prostate gland. "However, based on immunoblotting analyses in PC3 nuclear lysates and human prostate cancer cells, we propose that RUNX2 localized in the nucleus of cancer tissue is mostly phosphorylated (lane 2); c) Diffuse distribution of Smad-5 was observed in normal and prostate carcinoma sections." (PMID 22966907, 2012). "It has been reported in prostate cancer that integrin αvβ3 and CD44 pathways function in osteoclastogenesis via a RUNX2/Smad5-signaling axis, which provides evidence for RUNX2-related bone destruction in MM." (PMID 36897488, 2023).
renal fibrosis (2 papers, 2022 to 2024). A final common manifestation of a wide variety of chronic kidney diseases characterized by glomerulosclerosis and tubulointerstitial fibrosis. "The expression of genes that promote renal fibrosis (Smad2, Smad3, Smad4, Shh, Dll1) was downregulated, while the expression of genes that inhibit renal damage (Smurf1, Smurf2, Smad1, Smad5, Smad6, Smad7) was increased in the WT+miPEP31 group (PEP1/2) compared with the WT+ cPEP (SCR1/2) group." (PMID 38992718, 2024).
anemia (1 paper, 2021). A reduction in the number of red blood cells, the amount of hemoglobin, and/or the volume of packed red blood cells. "It was even questioned following a study showing that flexed tailed mice also had a mutation of the Madh5/Smad5 gene, involved in the BMP pathway, which could explain the anemia and flexed-tail phenotype." (PMID 33494450, 2021).
cardiac hypertrophy (1 paper, 2025). "Infusion of Ang II for 2 weeks in mice induces the phosphorylation of Smad1 and Smad5 in the carboxyl-terminal, leading to cardiac hypertrophy, which is inhibited by BMPR2 inhibitor, LDN193189." (PMID 39506064, 2025). "Mice with BMPR2 knockout showed reduced Ang II-induced cardiac tissue growth, demonstrating that Ang II can transactivate BMPR2 to activate Smad1 and Smad5, resulting in cardiac hypertrophy." (PMID 39506064, 2025).
chronic lymphocytic leukaemia (1 paper, 2023). "In chronic lymphocytic leukaemia(CLL), the expression of SMAD1, SMAD5, and SMAD8 is significantly increased and their overexpression is associated with short patient survival." (PMID 37685308, 2023).
chronic myeloid leukemia (1 paper, 2016). "The significantly enriched pathways included chemokine signaling pathway (which involved CCL2), focal adhesion (which involved THBS1 and THBS2), TGF-beta signaling pathway (which involved THBS1, THBS2, SMAD5, and SMAD6) and chronic myeloid leukemia (which involved TGFBR2 and CCND1)." (PMID 27716259, 2016).
chronic pancreatitis (1 paper, 2020). A chronic inflammatory process causing damage and fibrosis of the pancreatic parenchyma. "Furthermore, the protein level of Bcl-2 and Smad5 in our animal chronic pancreatitis models were detected, and the result showed that Bcl-2 and Smad5 upregulated in chronic pancreatitis model and decreased while treated with SAHA, and negatively correlated with miR-15 or miR-16." (PMID 32524326, 2020). "And we proved that Bcl-2 and Smad5 were the target genes of miR-15 and miR-16, which illustrated how HDAC inhibition alleviated the apoptosis and fibrogenesis of PSCs in chronic pancreatitis." (PMID 32524326, 2020).
cognitive disease (1 paper, 2022). "Interestingly, when we considered proteins which were significantly different in their SD between the healthy old and the old with cognitive disease and between the healthy young and healthy old, there were just 4 such proteins: Smad5, uPAR, FADD, and TGFBR1." (PMID 35999337, 2022).
colitis (1 paper, 2012). Inflammation of the colon. "Taken together, our findings suggest that the inhibitory effect of TNFα on hepcidin expression during DSS colitis is mediated by down-regulation of Smad1 protein (and possibly Smad5 and Smad8) and consequent interference with BMP-activated signals." (PMID 22675442, 2012).
diabetes (1 paper, 2024). "Therefore, altering pHc or inhibiting the nuclear export of Smad5 may alleviate insulin deficiency, suggesting that Smad5 could serve as a potential therapeutic target for diabetes treatment." (PMID 39578779, 2024).
endometriosis (1 paper, 2024). The growth of functional endometrial tissue in anatomic sites outside the uterine body. "We focused on the roles of BMP/SMAD1/5 signaling given that we observed altered expression of BMP ligands (BMP4, BMP6) as well as decreased expression of canonical SMAD1/SMAD5 targets in the decidualizing stromal cells from individuals with endometriosis." (PMID 38402336, 2024).
glioblastoma (1 paper, 2021). The most malignant astrocytic tumor (WHO grade IV). "It was shown that the Smad5 gene knockdown significantly blocks BMP7-increased p75NTR protein expression in human LN18 glioblastoma cells." (PMID 34357080, 2021). "In this BMP7 event, we further demonstrated that p75NTR could be upregulated in glioblastoma cells by Smad5 signaling." (PMID 34357080, 2021). "Based on this interesting finding, the present study further found that the endogenous and exogenous BMP7 stimulations indeed have an important role to promote the transmigration and migration capabilities of glioblastoma in human LN18/LN229 glioblastoma cells through Smad5-p75NTR pathway." (PMID 34357080, 2021). "Overall, the present study finds that the invasion-promoting activity of BMP7 might be an autocrine stimulation of glioblastoma and this effect could be regulated by Smad5-p75NTR signaling." (PMID 34357080, 2021). "Moreover, Smad5-specific siRNA could effectively attenuate the endogenous Smad5 expression level of human LN18 glioblastoma cells." (PMID 34357080, 2021). "The present study has found an autocrine BMP7 effect on glioblastoma transmigration and migration in human LN18 glioblastoma cells through Smad5, but not Smad1, and p75NTR signaling pathway." (PMID 34357080, 2021). "Finally, we determined whether Smad5 and p75NTR are involved in regulating the BMP7 effect on human LN18 glioblastoma cell transmigration and migration." (PMID 34357080, 2021). "Smad5 or p75NTR gene knockdown could significantly attenuate the transmigration level of human LN18 glioblastoma cells with and without BMP7 treatment." (PMID 34357080, 2021).
heart failure (1 paper, 2018). Inability of the heart to pump blood at an adequate rate to meet tissue metabolic requirements. "VIP (vasoactive intestinal peptide), cardioprotective in heart failure, and SMAD5, which has anti-apoptotic actions in cardiac myocytes were upregulated." (PMID 29556499, 2018).
insomnia (1 paper, 2025). A sleep disorder characterized by difficulty in falling asleep and/or remaining asleep. "For Sleeplessness/Insomnia, the top signal was a Bonferroni-significant association with the expression of SMAD5 in blood (eQTLGen; PSMR = 3.25 × 10−11), complemented by pQTL evidence linking it to HEXIM2 (deCODE; PSMR = 3.46 × 10−10)." (PMID 41296471, 2025). "The identification of PCYOX1 protein levels as a top hit for chronotype, and SMAD5 expression for insomnia, nominates these genes as high-priority candidates for understanding sleep–wake regulation." (PMID 41296471, 2025).